MT2A (metallothionein 2A)
Diseases named in the same sentence as MT2A in open-access papers (continued):
Sharing a sentence is not in itself a finding about the gene and the disease.
lung carcinoma (8 papers, 2013 to 2024). "Upregulation of MT2A is also associated with poor survival in patients with nonsmall-cell lung cancer." (PMID 39495117, 2024). "Further studies are needed to verify association of rs1799750 in MMP-1, rs243865 in MMP-2, rs11568818 in MMP-7, rs2252070 in MMP-13 and rs28366003 in MT2A with breast, colon and lung cancers." (PMID 32765800, 2020). "This study investigated the expression of Nrf2 and of Nrf2-targeted genes (NQO1 and GCLC) and the genes for the metallothionein (MT) isoforms (MT-1A and MT-2A) in human lung cancer and cancer-surrounding tissues." (PMID 23947958, 2013). "Downregulation of MT-1A and MT-2A was found in the surgical stage of lung cancers, whereas the NRF2-targeted gene NQO1 tended to increase." (PMID 23947958, 2013). "The levels of MT2A mRNA are considered as a marker of poor prognosis for lung cancer patients." (PMID 37920509, 2023). "However, a previous study has found that MT2A expression levels in lung cancer tissues are significantly downregulated compared to paracancerous tissues." (PMID 35642057, 2022). "In our study we did not detect significant correlation of rs28366003 in MT2A with breast, colon or lung cancer risk, although we observed higher frequency of AG and GG genotypes in colon and lung cancer cases in comparison to controls (12.7% vs. 7.3 and 12.6% vs. 9.5%, respectively)." (PMID 32765800, 2020). "By contrast, expression of the genes for M)-1A, MT-2A, and the metal transcription factor MTF-1 were three-fold to four-fold lower in lung cancers." (PMID 23947958, 2013). "In lung cancer, the five most important mRNAs were HBB, HBA2, MT2A, ZFP36, and DUSP1." (PMID 39495117, 2024).
ovarian carcinoma (8 papers, 2013 to 2025). A malignant neoplasm originating from the surface ovarian epithelium. "Some evidence indicated that increased MT2A expression is important for cancer progression, and MT2A is initially proposed as a proto-oncogene in breast, esophageal, prostate, and ovarian cancers, associated with malignancy and poor prognosis." (PMID 23870553, 2013). "Bioinformatic analysis revealed that NDRG1, CYBRD1, and MT2A expressions upregulated and were associated with poor prognosis of ovarian cancer patients in the platinum-based treatment group, whereas upregulation of ERBB4 and ANK3 correlated with improved prognosis." (PMID 38987777, 2024). "Another study on high-grade epithelial ovarian cancer identified that MT2A expression was increased after chemotherapy, highlighting its potential association with drug resistance." (PMID 38987777, 2024). "In addition, in vitro experiments showed that NDRG1, CYBRD1, and MT2A played a role in ovarian cancer cisplatin resistance." (PMID 38987777, 2024). "Notably, cell experiments were performed to validate the roles of NDRG1, CYBRD1, and MT2A in cisplatin resistance in ovarian cancer." (PMID 38987777, 2024). "CAOV3 HGSC cells were selected, due to uniquely restricted expression among all ovarian cancer cell lines of only MT2A and MT1X, with MT2A as the predominantly expressed metallothionein." (PMID 39858588, 2025).
hepatocellular carcinoma (7 papers, 2013 to 2024). A malignant tumor that arises from hepatocytes. "In contrast, it is down-regulated in gastrointestinal tumors and hepatocellular carcinomas, where MT2A is either inversely correlated or unrelated to mortality." (PMID 23870553, 2013). "The suppression of MT1 and MT2A in human hepatocellular carcinoma was related to the dephosphorylation (inactivation) of the transcription factor CCAAT/enhancer-binding protein (C/EBP) α through the PI3K/AKT signaling pathway rather than the gene hypermethylation." (PMID 30139373, 2018).
colon cancer (5 papers, 2013 to 2022). "In colon cancer group we observed that MMP-7 GG genotype as well as MT2A AG and GG genotypes were more frequent among cases than controls (18% vs 13.3 and 12.7% vs 7.3%, respectively)." (PMID 32765800, 2020). "Five SNPs, rs1799750 in MMP-1, rs243865 in MMP-2, rs11568818 in MMP-7, rs2252070 in MMP-13 and rs28366003 in MT2A has been studied in various cancers including breast, lung and colon cancer, but results were ambiguous." (PMID 32765800, 2020). "In the present study we analyzed whether polymorphisms rs28366003 in MT2A, rs1799750 in MMP-1, rs243865 in MMP-2, rs11568818 in MMP-7 and rs2252070 in MMP-13 genes are associated with the risk of breast, lung or colon cancer among polish subjects." (PMID 32765800, 2020). "The aim of this study was to investigate association of polymorphisms rs1799750 in MMP-1, rs243865 in MMP-2, rs11568818 in MMP-7, rs2252070 in MMP-13 and rs28366003 in MT2A, together with serum Zn level, with occurrence of breast, lung and colon cancer in Poland." (PMID 32765800, 2020). "In addition, MT2A suppression is frequently observed in GC, and similar data was reported in hepatocellular and colon cancer." (PMID 23870553, 2013). "On the other hand, it also indicated that two genes, namely, MT2A and MAFF, might act an important role in the development and progression of colon cancer and the prognostic model based on these genes would be valuable for clinical application." (PMID 34917146, 2021).
diabetes (5 papers, 2015 to 2023). "These MT2A-Tg NOD mice displayed normal glucose tolerance before diabetes induction, and their islets had normal expression of ER stress genes (Hspa5, Ddit3)." (PMID 33652748, 2021). "Others have been associated with diabetes (ZBED3), asthma (EMID2), and cancer (FBXO3, HOOK2, MT2A, EIF3E, RPH3AL, PTRF, MT1M, STK32A)." (PMID 25748564, 2015). "Surprisingly, in comparison to control NOD mice, MT2A-Tg NOD mice exhibited a marked acceleration of diabetes onset after cyclophosphamide injection (used to accelerate and synchronize diabetes development in this model)." (PMID 33652748, 2021). "Moreover, spontaneous diabetes onset was also accelerated in male, but not female, MT2A-Tg NOD mice." (PMID 33652748, 2021).
esophageal cancer (5 papers, 2015 to 2024). A primary or metastatic malignant neoplasm involving the esophagus. "High-expressed MT2A is associated with poor esophageal cancer prognosis and induces malignant physiological processes of cancer cells." (PMID 38409358, 2024). "TCGA database was used to analyze the relationship between expression of MTA2, MT1E and MT1X in esophageal cancer and prognosis and survival, and the analysis results showed that low expression of MT2A, MT1E and MT1X was associated with poorer overall survival." (PMID 36466860, 2022). "MT2A, MT1E, MT1X expression is associated with CD8+ T cell infiltration in malignant tumors including esophageal cancer." (PMID 36466860, 2022). "The expression of MT2A, MT1E and MT1X in esophageal cancer patients and normal persons was detected by TCGA database, and it was found that the expression of MT2A, MT1E and MT1X in esophageal cancer patients was significantly reduced." (PMID 36466860, 2022). "GEPIA database analysis, MT1E, MT1X molecule transcription levels in esophageal cancer patients and normal control group MT2A, MT1E, MT1X molecule." (PMID 36466860, 2022). "The expression of MT2A, MT1E and MT1X in esophageal cancer patients and normal controls was detected by TCGA database, and it was found that the expression of MT2A, MT1E and MT1X in esophageal cancer patients was significantly reduced, which was associated with poor prognosis." (PMID 36466860, 2022). "They showed that ECRG2 directly interacted with metallothionein 2A (MT2A), and the ECRG2-mediated modulation of MT2A function was thought to be a possible mechanism via which ECRG2 suppresses esophageal cancer cell growth." (PMID 38892042, 2024). "The expression of MT2A, MT1E and MT1X in esophageal carcinoma and their relationship with CD8+ T cell infiltration were detected." (PMID 36466860, 2022).
Obesity (5 papers, 2019 to 2025). Accumulation of substantial excess body fat. "For instance, human studies demonstrated that the level of MT-2A mRNA (a major metallothionein isoform in humans) is increased in the WAT of obese patients, which suggests that MT-2A could be a pro-obesity factor." (PMID 40362306, 2025).
osteosarcoma (5 papers, 2015 to 2024). A usually aggressive malignant bone-forming mesenchymal neoplasm, predominantly affecting adolescents and young adults. "Four chosen osteosarcoma cell lines exhibit increased sensitivity to several chemotherapeutic agents when MT2A is silenced, which promotes the effectiveness of chemotherapeutic agents." (PMID 39061894, 2024). "B/My MPAL blast cells from induction failure patients showed high expression of MT2A and FKBP5 genes that are associated with chemoresistance in osteosarcoma, solid cancers, and ALL." (PMID 37845689, 2023). "This reinforced our previously reported correlation between MT2A mRNA level in tumour samples at diagnosis and overall survival in patients with osteosarcoma." (PMID 31444479, 2019). "The present study first assesses the predictive value of MT2A expression level in response to various chemotherapy agents using a panel of osteosarcoma cell lines." (PMID 31444479, 2019). "In summary, this study identified the key role of high MT2A expression level in the resistance of osteosarcoma cells to chemotherapeutic drugs." (PMID 31444479, 2019). "Taken together, these results indicate that MT2A mRNA level correlate with cell resistance to chemotherapy-based therapies currently used in osteosarcoma." (PMID 31444479, 2019). "We first determined the expression level of MT2A in a panel of eight osteosarcoma cell lines by real-time quantitative RT-PCR." (PMID 31444479, 2019). "We showed that MT2/MT2A silencing enhanced cytotoxic action of current chemotherapeutic drugs on osteosarcoma cells in vitro, reflected by the lowering of IC50 values for all tested drugs." (PMID 31444479, 2019). "We previously reported that high MT2A mRNA level in tumour tissue at diagnosis correlates with poor response to chemotherapy and poorer outcome in a small cohort of osteosarcoma patients, suggesting a prognostic significance." (PMID 31444479, 2019). "Taken together, these results indicate that osteosarcoma cells rather promote MT2A neo-synthesis than trigger the glutathione-dependent detoxication in response to cisplatinum, doxorubicin, mafosfamide, or methotrexate." (PMID 31444479, 2019). "We determined the migration speed of our panel of osteosarcoma cell lines both in basal culture conditions, and combined them to MT2A mRNA level." (PMID 31444479, 2019). "Our results thus support a model whereby MT2A contributed to lowering the drug cytotoxic effects and could be a valuable therapeutic target to improve osteosarcoma sensitivity to chemotherapy." (PMID 31444479, 2019). "The second significant finding of our study is the proof of concept that MT2A could also be a valuable therapeutic target to improve osteosarcoma sensitivity to chemotherapy." (PMID 31444479, 2019). "Taken together, these data show that MT2A could be considered as a therapeutic target to prevent or reduce osteosarcoma resistance to chemotherapy." (PMID 31444479, 2019). "In conclusion, we demonstrated that MT2A could be considered as a predictive biomarker of the efficacy of chemotherapy for patients with osteosarcoma, and as a potential therapeutic target to develop novel treatment strategy to prevent or de-escalate chemo-resistance in osteosarcoma." (PMID 31444479, 2019). "Taken together, our data showed that MT2A contributes to chemotherapy resistance in osteosarcoma, and could be considered as a predictive indicator at diagnosis for osteosarcoma responsiveness to current chemotherapy regimen, whatever their mechanism of action." (PMID 31444479, 2019). "In our panel of osteosarcoma cell models, IC50 values were heterogeneous from one cell line to another, but overall correlated to the MT2/MT2A mRNA level." (PMID 31444479, 2019). "Our results show that MT2A level could be used as a predictive biomarker of resistance to chemotherapy, and provide with preclinical rational for MT2A targeting as a therapeutic strategy for enhancing anti-tumour treatment of innate chemo-resistant osteosarcoma cells." (PMID 31444479, 2019).
Alzheimer disease (4 papers, 2016 to 2023). A progressive, neurodegenerative disease characterized by loss of function and death of nerve cells in several areas of the brain leading to loss of cognitive function such as memory and language. "Mathys and colleagues investigated the frontal cortex of human late onset Alzheimer disease using snRNAseq and showed expression of MT2A, MT1G, and MT1E in astrocytic cluster Ast1." (PMID 32070434, 2020). "Alzheimer’s disease is triggered by the deposition of insoluble extracellular b-amyloid (Ab) plaque, and MT2A is capable of protecting against Ab aggregation and toxicity for therapeutic approach to Alzheimer’s disease." (PMID 27608012, 2016). "In relation to this, MT2A is considered a key player in the maintenance of immune homeostasis and its involvement as a neuroprotective factor has been described in different neurodegenerative diseases such as Parkinson's disease, Alzheimer's disease, or amyotrophic lateral sclerosis." (PMID 37580456, 2023).
atherosclerosis (4 papers, 2013 to 2025). A disease characterized by the build-up of fatty material and calcium deposition in the arterial wall resulting in partial or complete occlusion of the arterial lumen. "In fact, fetal high-density lipoprotein, which is associated with the inhibition of atherosclerosis, reduces the expression of MT-1X and MT-2A in human placental endothelial cells." (PMID 27563876, 2016). "The KGs of T cells involved in the effects of hawthorn on the PVAT microenvironment in atherosclerosis were CCL3, CCL4, MT2A, and MT1X." (PMID 40824771, 2025).
gastric adenocarcinoma (4 papers, 2022 to 2023). "Designing a case-control study including gastric adenocarcinoma and gastritis patients with and without Helicobacter pylori infection would lead to determinate of the correlations between ptk2 and mt2a genes expression with H. pylori infection in gastric antral epithelial cells." (PMID 36060520, 2022).
non-small cell lung carcinoma (4 papers, 2015 to 2022). A group of at least three distinct histological types of lung cancer, including non-small cell squamous cell carcinoma, adenocarcinoma, and large cell carcinoma. "In addition, another study has demonstrated that the upregulation of MT2A is associated with poor survival in patients with non-small-cell lung cancer." (PMID 35642057, 2022).
bladder cancer (3 papers, 2022 to 2025). "Further RT-qPCR analysis of paired human bladder tissues indicated that MT2A mRNA expression is significantly higher in normal bladder tissues than bladder cancer tissues, verifying the role of MT2A on tumor suppression." (PMID 36009228, 2022). "The RT-qPCR assays showed T24 cells with the highest and RT4 cells with the lowest MT2A levels among the four bladder cancer cell lines as compared to normal bladder epithelial cells, HBdEC." (PMID 36009228, 2022). "In this study, we aimed to elucidate the expression and function of MT2A in human bladder carcinoma cells and to examine the antioxidant and antitumor activity of MT2A in bladder cancer in vitro and in vivo." (PMID 36009228, 2022). "Further work is needed to confirm the application of MT2A and related inducers against tumorigenesis and oxidative consequences of bladder cancer." (PMID 36009228, 2022). "The antioxidative activity of HO-1 and its cooperation with MT2A in bladder carcinoma cells have yet to be disclosed." (PMID 36009228, 2022). "We continued to evaluate the MT2A antitumor activity of bladder carcinoma cells in vitro and in vivo." (PMID 36009228, 2022). "As far as we are concerned, this is the first study providing laboratory values to demonstrate the tumor-suppressive role of MT2A in human bladder carcinoma cells." (PMID 36009228, 2022). "The xenograft study also presented that mock-knockdown bladder carcinoma HT1376 cells grew slower than the MT2A knockdown bladder carcinoma HT1376 cells in vivo." (PMID 36009228, 2022). "Knockdown of MT2A increased invasion and cell growth in vitro and in vivo, whereas ectopic overexpression of MT2A had the reverse effect in bladder carcinoma cells." (PMID 36009228, 2022). "We evaluated MT2A in bladder carcinoma cells in terms of the mechanisms of regulation and the underlying functions." (PMID 36009228, 2022). "Further flow cytometry assays indicated that endogenous ROS was upregulated when MT2A was knocked down in bladder carcinoma cells." (PMID 36009228, 2022). "Immunoblot assays revealed that CAPE treatment (20 μM) upregulated MT2A and HO-1 expressions in bladder carcinoma T24 cells; moreover, knockdown of MT2A attenuated the activation of CAPE on HO-1 protein levels (left)." (PMID 36009228, 2022). "Our findings suggest that MT2A is an antioxidative as well as an antitumor gene in bladder carcinoma cells." (PMID 36009228, 2022). "Reporter assays using the MT2A and HO-1 reporter vectors with a specific human MT2A and HO-1 promoters, respectively, revealed that CAPE induced MT2A and HO-1 reporter activities dose dependently in bladder carcinoma HT1376 and TSGH-8301 cells." (PMID 36009228, 2022). "In the present study, our results indicated that knockdown of MT2A induced endogenous ROS; in addition, ectopic overexpression of MT2A MT2A blocked H2O2-induced ROS generation in bladder carcinoma cells." (PMID 36009228, 2022). "CAPE induces MT2A and HO-1 expressions to downregulate endogenous ROS in bladder carcinoma cells; however, the induction of CAPE on HO-1 expression is MT2A dependent." (PMID 36009228, 2022). "We determined the antioxidant response of overexpression of MT2A in human bladder carcinoma HT1376 cells." (PMID 36009228, 2022). "Collectively, these results are the first study indicating that MT2A modulated HO-1 expression; moreover, CAPE induced MT2A and HO-1 to alleviate endogenous ROS and the activation of CAPE on HO-1 is dependent on MT2A in bladder carcinoma cells." (PMID 36009228, 2022). "In the present study, our results demonstrated that CAPE treatment upregulated MT2A and HO-1 expressions to alleviate endogenous ROS in bladder carcinoma cells which is consistent with other studies in HL-60 and H9c2 cells." (PMID 36009228, 2022). "Collectively, our results indicated that MT2A is acting as an antioxidant and also a tumor suppressor in human bladder carcinoma cells." (PMID 36009228, 2022).